CCR9 (C-C motif chemokine receptor 9)
Diseases named in the same sentence as CCR9 in open-access papers (continued):
Sharing a sentence is not in itself a finding about the gene and the disease.
acute lymphoblastic leukemia (9 papers, 2013 to 2023). Leukemia with an acute onset, characterized by the presence of lymphoblasts in the bone marrow and the peripheral blood. "A previous study showed that CCR9 induces tumor migration via loss of PTEN in T-lineage acute lymphoblastic leukemia models." (PMID 34863167, 2021). "We performed the DisGeNET GO enrichment analysis to get the disease phenotype associated with CCR9 overexpression and found its enrichment in leukemic pathways including precursor cell lymphoblastic leukemia, acute promyelocytic leukemia, and acute lymphocytic leukemia." (PMID 37745085, 2023). "Monoclonal antibody (92R) tested in NSG mice to target T cell acute lymphoblastic leukemia cells strongly inhibited tumor growth via binding to the C-C chemokine receptor type 9 (CCR9) N-terminal domain." (PMID 33603749, 2020). "CCR9 is as an interesting target for the treatment of human CCR9+-T cell acute lymphoblastic leukemia, since its expression is limited to immature cells in the thymus, infiltrating leukocytes in the small intestine and a small fraction of mature circulating T lymphocytes." (PMID 29434597, 2018). "In acute lymphoblastic leukemia, Notch1 regulates cell proliferation and migration through CCR5 and CCR9, and in multiple myeloma Notch regulates CXCR4." (PMID 28137279, 2017). "Moreover, CCR9 is highly expressed in malignancies, such as lung cancer, breast cancer, ovarian cancer, melanoma, and T-cell acute lymphoblastic leukemia (T-ALL)." (PMID 36810516, 2023).
Sjögren's syndrome (9 papers, 2018 to 2024). "CCR9+ Tfh-like pathogenic T helper (Th) cells are elevated in patients with primary Sjögren’s syndrome (pSS) and indicated to play a role in pSS immunopathology." (PMID 34386009, 2021). "Here we demonstrate the transcriptome of CCR9-expressing pathogenic T helper cells from primary Sjögren’s syndrome patients and healthy controls and identify CCL5 as a novel effector molecule of CCR9+ Th cells." (PMID 34386009, 2021). "Mucosal-associated invariant T (MAIT) cells might play a role in B cell hyperactivity and local inflammation in primary Sjögren’s syndrome (pSS), just like previously studied mucosa-associated CCR9+ and CXCR5+ T helper cells." (PMID 36505431, 2022). "In Sjogren's syndrome patients, CCR9+ CXCR5− T cells from the blood produced CXCL13 (in addition to IL-21 ), albeit at lower levels than was produced by CXCR5+ cells." (PMID 30190721, 2018). "CCR9 + T helper (Th) cells can induce Sjögren‐like symptoms in mice and both CCR9 + Th cells and their ligand CCL25 are increased in the salivary glands of primary Sjögren's syndrome (pSS) patients." (PMID 31733111, 2020).
influenza infection (8 papers, 2016 to 2025). "In mice, lung-derived CCR9+CD4+ T cells migrate to the small intestine via the CCL25/CCR9 axis during influenza infection, contributing to dysbiosis and IL-15-driven Th17 polarization that exacerbates IL-17A-mediated intestinal injury." (PMID 40872830, 2025). "After influenza infection, the percentage and number of CCR9+CD4+ T cells increase in the lungs, which in turn specifically migrate to the intestinal mucosa through CCL25-CCR9 chemokine axis, producing interferon (IFN)-γ and causing intestinal damage." (PMID 37571299, 2023). "Specifically, during influenza CCR9+ CD4+ T cells are recruited from the lung to intestinal tissues." (PMID 27148490, 2016). "SARS-CoV-2-specific T cells co-expressed CCR9 and Integrin β7, which showed a variable pattern but as a group was more abundant within SARS-CoV-2 tetramer+ populations compared to influenza-specific T cells or total memory cells." (PMID 35857619, 2022). "CCR9, as part of a CCL25-CCR9 chemokine axis, has been shown to mediate gut-specific recruitment of lung IFN-γ-producing CCR9+CD4+ T-cells in influenza, contributing to the gut injury observed in viral infection." (PMID 33828231, 2021). "The intestinal microbiota composition was shown to be altered in mice with influenza infection, which was mediated by IFN-γ produced by lung-derived CCR9+CD4+ T cells recruited into the small intestine." (PMID 31750262, 2019). "CCL25, a chemokine ligand for CCR9, has been shown to play both pro- and anti-inflammatory roles in various diseases, while CCL3 and its receptor CCR5 involvement in leukocyte recruitment into the airway to up-regulate antiviral responses in influenza infection." (PMID 39331702, 2024).
ulcerative colitis (8 papers, 2011 to 2025). An inflammatory bowel disease involving the mucosal surface of the large intestine and rectum. "In contrast, specimens from patients with ulcerative colitis refractory to medical therapy contained significantly more CCR9 expressing CD4+ (92.6 ± 4.1%; p < 0.001) and CD8+ T-cells (34.3 ± 3.8%; p = 0.013) than non-inflamed colon." (PMID 26873648, 2016). "In addition, we determined the effect of CCR9 pharmacological inhibition in the mdr1a−/− mouse model of ulcerative colitis." (PMID 26457007, 2015). "This suggests that blocking CCL25/CCR9 interactions in ulcerative colitis patients may lead to an inefficiency in resolving intestinal inflammation or, at worst case, even exacerbated IBD symptoms." (PMID 21283540, 2011). "Thus, our findings are of high relevance for clinical care of human IBD as they point to potential detrimental effects of CCR9-blocking therapy for patients suffering from inflammation in the large intestine, as commonly observed in ulcerative colitis." (PMID 21283540, 2011). "In the mdr1a−/− mouse model of ulcerative colitis, increased colonic CCL25 protein levels were noted before any clinical manifestations of disease and correlated temporally with increases in the frequency of circulating CCR9+CD4+ T cells, which we used as a surrogate for intestinal inflammation." (PMID 26457007, 2015). "As CCL25/CCR9 interactions are currently considered dispensable for the regulation of inflammation in the large intestine, the therapeutic effect of the CCR9-antagonist has not been studied in ulcerative colitis." (PMID 21283540, 2011).
asthma (7 papers, 2013 to 2024). "Interestingly, when mice received food allergen-sensitized lymphocytes from CCR9–/– mice, the exacerbation of asthma caused by food allergen CD4+ lymphocytes was eliminated." (PMID 34490243, 2021). "Moreover, to better understand the mechanism underlying the food allergy-induced aggravation of asthma and the role of CCR9, they performed adoptive transfer of CD4+ T cells from food-allergic mice into naïve mice, which were subsequently sensitized to house dust mites." (PMID 34490243, 2021). "There is a single published study that used a murine model to investigate the effect of an active and knocked-down CCR9 on asthma-induced lung inflammation." (PMID 37547597, 2023). "The CCR9/CCL25 axis functions in homeostasis, inflammation, and inflammation-associated diseases including early respiratory allergic inflammation, asthma, chronic inflammatory bowel diseases, and organ fibrosis." (PMID 35862771, 2022). "Increasing evidence has supported the role of chemokine receptors in allergic airway inflammation; however, the involvement of CCR9 in asthma remains unclear." (PMID 27795621, 2016). "CCR9/CCL25 signal can interact with CD226 signaling to activate asthmatic NKT cells, leading to airway hyperresponsiveness and inflammation, aggravating asthma." (PMID 34490243, 2021). "CCR9/CCL25 is participated in many inflammatory diseases, including CVD, hepatitis, RA, IBD, and asthma." (PMID 34490243, 2021).
Autoimmunity (7 papers, 2018 to 2025). The occurrence of an immune reaction against the organism's own cells or tissues. "CCR9+ DCs are implicated in regulating inflammation, food allergy, alloimmunity, and autoimmunity." (PMID 33123124, 2020). "CCR9 + T helper cells are known to accumulate in the pancreas and other accessory organs of the digestive system during autoimmunity and other chronic inflammation." (PMID 33154424, 2020). "In this review, we examine the phenotypes, distributions, and interactions of CCR9+ DCs with other immune cells, elucidating their functions and role in inflammation and autoimmunity." (PMID 33123124, 2020). "In this study, we analyzed the characteristics of CCR9+ Th and T follicular helper (Tfh) cells in GIT associated lymphoid tissues in health, chronic inflammation and autoimmunity." (PMID 30662436, 2018). "A greater understanding of the CCR9 expressing Th cells in immunity and autoimmunity will facilitate the generation of new strategies for the treatment of IBD and inflammatory diseases that affect the accessory organs of the digestive system." (PMID 30662436, 2018). "CCR9/CCL25 forms a signaling axis critical for T-cell homing to the small intestine that has been implicated in gut immune surveillance, IBD, gut innate immunity, and autoimmune disorders." (PMID 40894167, 2025). "Therefore, we examined CCR9+/− Th and CCR9+/− Tfh cells in two models of autoimmunity and inflammation, namely the NOD mouse and mice that have been made genetically deficient in IL-2 (Il2−/−mice)." (PMID 30662436, 2018). "However, our studies demonstrate that during autoimmunity and chronic inflammation, CCR9+ T helper cells also infiltrate the pancreas and other accessory organs of the digestive system and are crucial to the destruction of these tissues." (PMID 30662436, 2018). "However, despite the important role of the GIT in both immunity and autoimmunity, the nature of CCR9-expressing cells in GIT lymphoid organs and their role in chronic inflammatory diseases remains unknown." (PMID 30662436, 2018). "Taken together, the findings provide evidence that CCR9+ Tfh cells and Th cells from the GIT exhibit plasticity and can accumulate in distal accessory organs of the digestive system where they may participate in autoimmunity." (PMID 30662436, 2018).
colon cancer (7 papers, 2015 to 2025). "The IHC results from HPA also revealed that the expression level of CCR9 was significantly higher in colon cancer than in normal colon tissue." (PMID 38049474, 2023). "CCR9−/− mice showed a trend to develop less tumors than CCR9+/− mice (p=0.0693) and developed significantly less tumors of 2–3 mm in size, indicating that expression CCR9 may favor colon cancer development." (PMID 40305493, 2025). "Remarkably, the CD4/CD8 ratio, which indicates the immune state, is significantly lower in the tumor and peri-tumoral zone of CCR9−/−, suggesting that CCR9 expression controls the immune balance in colon cancer, and showing an enrichment of CD8+ T cells when CCR9 is absent." (PMID 40305493, 2025).
ileitis (7 papers, 2011 to 2021). "The oral CCR9 antagonist CCX282-B/vercirnon was successfully used in the TNFΔARE ileitis mouse model as well as for the treatment of moderate-to-severe CD in a phase II study." (PMID 34017333, 2021). "Blocking either CCR9 or CCL25 in mice treated with TNFα or in the SAMP1/YitFc model of ileitis demonstrated reduction of leukocyte migration to the small intestine and strong inhibition of inflammation." (PMID 34017333, 2021). "Based on data from mice model, CCR9 seems to induce migration of Tregs to the intestine and administration of antibodies against CCR9 in tumor necrosis factor Δadenosine uracil-rich element mice exacerbated ileitis." (PMID 23977348, 2013). "Interference with the CCR9/CCL25 axis has been shown to improve disease symptoms and tissue inflammation in mouse models of ileitis such as the SAMP-1/Yit model and the TNF-ΔARE model." (PMID 26457007, 2015). "Blockade of CCR9 or CCL25 does not attenuate inflammation during the late stages of chronic murine ileitis." (PMID 27424033, 2016). "Indeed, targeting the CCR9/CCL25 axis has been shown to be of benefit in the TNF-ΔARE and SAMP-1/YIT models of ileitis." (PMID 26457007, 2015).
pancreatic cancer (7 papers, 2015 to 2025). "Previous research has revealed that CCR9 can activate the Wnt/β-catenin signaling pathway to enhance invasiveness and chemoresistance in pancreatic cancer." (PMID 34863167, 2021). "Further, β-catenin activation induced by CCR9 increased the expression of Cyclin E1, Cyclin D1, and E-Cadherin to increase the lethal dose of gemcitabine in pancreatic cancer, suggesting that CCR9/β-catenin signaling enhances pancreatic cancer chemoresistance." (PMID 26879872, 2016). "The CCL25/CCR9 axis reportedly enhances cell proliferation, invasion, and drug resistance via β-catenin activation in pancreatic cancer cells, suggesting that β-catenin signaling may also be involved in T-ALL cell migration and invasion." (PMID 28380463, 2017). "Most cancer cells upregulate CCR9 to mediate metastasis, and some cancers secrete CCL25 in a paracrine fashion; these cells include pancreatic cancer PSCs and PANC-1 cells, which then induce metastasis by binding the secreted CCL25 to CCR9 receptors in the nearby tissues." (PMID 26879872, 2016). "Taken together, these data show that 92R mAb could also impair progression of non-hematopoietic CCR9+ tumors, in particular of pancreatic tumors." (PMID 35967322, 2022).
atherosclerosis (6 papers, 2013 to 2024). A disease characterized by the build-up of fatty material and calcium deposition in the arterial wall resulting in partial or complete occlusion of the arterial lumen. "In the cardiovascular system, CCR9 was first found to be associated with the pathophysiology of atherosclerosis, and inhibition of CCR9 by RNA interference in apoE-deficient mice significantly retarded the development of atherosclerosis." (PMID 27585634, 2016). "In relation to CVD, in a mouse model of atherosclerosis, the presence of monocytes and resident macrophages expressing CCR9 with characteristics of plaque-foaming cells was observed." (PMID 38247848, 2024). "Further, CCR9-CCL25 signaling has been shown to be pro-atherogenic, since inhibition of CCR9 led to a delay in the development of atherosclerosis in Apoe-/- mice." (PMID 38179045, 2023). "On the contrary, CCR9+ pDCs have been reported to be tolerogenic and CCR9 loss to be deleterious in the development of atherosclerosis, which suggests that CCR9 is not necessarily a marker of inflammation." (PMID 38247848, 2024). "Therefore, one cannot exclude the possibility that CCR9+ monocytes play a protective role in atherosclerosis." (PMID 38247848, 2024).
autoimmune disease (6 papers, 2011 to 2025). A disorder resulting from loss of function or tissue destruction of an organ or multiple organs, arising from humoral or cellular immune responses of the individual to their own tissue constituents. "A review described the involvement of CCL25/CCR9 in various pathological processes, such as inflammatory diseases, autoimmune diseases, metabolic disorders, and tumorigenesis." (PMID 39411316, 2024). "More recently, we described a T helper (Th) cell subset based upon expression of CCR9 (termed Tccr9 cells) that contribute to the regional specification of organ-specific autoimmune disease." (PMID 30662436, 2018). "CD4+ CCR9+ T helper cells express high amounts of interleukin 21 and induce T cell costimulatory factor, transcription factor B cell CLL/lymphoma 6 (Bcl-6), and Maf, which are local features of autoimmune diseases that affect the accessory organs of the digestive system." (PMID 34490243, 2021).
lung adenocarcinoma (6 papers, 2015 to 2025). A carcinoma that arises from the lung and is characterized by the presence of malignant glandular epithelial cells. "Kaplan-Meier survival analysis was performed to investigate the association between CCR9 expression and the overall survival (OS) of lung adenocarcinoma patients." (PMID 32308544, 2020). "According to Kaplan-Meier survival analysis, expression of CCR9 was negatively associated with OS in lung adenocarcinoma, as the patients with positive CCR9 expression exhibited a poorer OS." (PMID 26168791, 2015). "The expression of CCR9 is also increased in lung adenocarcinoma compared with normal lungs, and the expression was positively correlated with tumor size and lymph node metastasis and predicts the poor prognosis in patients with lung adenocarcinoma." (PMID 39768150, 2024). "A study of 76 lung adenocarcinoma biopsies showed that high levels of CCR9 detected by immunohistochemistry, which occurred in 63% of samples, correlated with worse overall survival." (PMID 35740564, 2022). "In this study, we found that increased expression of CCR9 was correlated with distant metastasis in lung adenocarcinoma patients." (PMID 32308544, 2020). "Consistantly, our study also demonstrated that increased CCR9 expression was detected in lung adenocarcinoma tissues." (PMID 32308544, 2020). "This study will provide more evidence for us to further study the application of CCR9 as an effective and novel strategy in inhibiting the metastasis of lung adenocarcinoma." (PMID 32308544, 2020). "High expression of CCR9 was correlated with distant metastasis and poor overall survival in lung adenocarcinoma patients." (PMID 32308544, 2020). "In this study, we, for the first time, reported the prognostic value of CCR9 expression for postoperative patients with lung adenocarcinoma." (PMID 26168791, 2015). "Such an increased CCR9 expression was associated with larger tumor size, positive lymph node metastasis, advanced clinical stage and poor prognosis among patients with lung adenocarcinoma, suggesting that CCR9 might be a novel prognostic biomarker for lung adenocarcinoma." (PMID 26168791, 2015). "Immunohistochemical analysis of CCR9 expression was performed on 144 lung adenocarcinoma tissues and 30 adjacent normal lung parenchymal tissues." (PMID 26168791, 2015). "In the present study, we aimed to evaluate the expression and possible prognostic role of CCR9 in lung adenocarcinoma." (PMID 26168791, 2015). "In the present study, we aimed to investigate the expression of CCR9 in lung adenocarcinoma tissue and its correlations with clinicopathological characteristics." (PMID 26168791, 2015). "Taken together, we, for the first time, investigated the prognostic impact of CCR9 on lung adenocarcinoma." (PMID 26168791, 2015). "Interestingly, our current founding showed that higher expression of CCR9 could be linked with tumor size in lung adenocarcinoma; the positive expression rate of CCR9 (58/68, 85.3 %) in tumor tissue with lymph node metastasis was greater than that without lymph node metastasis (47/76, 61.8 %)." (PMID 26168791, 2015). "Except for TNM stage, CCR9 expression emerged as an independent prognostic indicator of OS for patients with lung adenocarcinoma." (PMID 26168791, 2015). "In the present study, we analyzed the expression of CCR9 at the protein level in lung adenocarcinoma tissues and adjacent normal lung tissues." (PMID 26168791, 2015). "High level of CCR9 expression was detected in 105 (72.9 %) of the 144 lung adenocarcinoma samples, whereas it was detected only in 2 (6.7 %) of the 30 adjacent normal lung tissue samples." (PMID 26168791, 2015). "Multivariate analysis showed that the CCR9 expression was an independent prognostic factor for the OS of patients with lung adenocarcinoma." (PMID 26168791, 2015). "The expression of CCR9 was increased in lung adenocarcinoma tissue compared with normal lung tissue." (PMID 26168791, 2015).